IL6 (interleukin 6)
Diseases named in the same sentence as IL6 in open-access papers (continued):
Sharing a sentence is not in itself a finding about the gene and the disease.
ulcerative colitis (continued). "One study in Crohn's disease reported a significant decrease in proinflammatory cytokines (IL-1, IL-6 and TNF-alpha) and one study in ulcerative colitis reported a decrease in IL-6 with HBOT." (PMID 22417628, 2012). "Inhibition of disease-promoting cytokine pathways by CEP-33779 nearly rivaled that of standard-of-care treatments, strongly suggesting the use of this inhibitor in other IL-6-dependent diseases, such as Crohn's disease and ulcerative colitis." (PMID 21510883, 2011). "CRP levels could also be lowered due to a decreased expression of IL-6, and it has been reported that probiotic consumption lowers IL-6 expression in ulcerative colitis patients." (PMID 40859402, 2025). "In a DSS-induced murine ulcerative colitis UC model, daily gavage with dehydrocostus lactone at 20, 15, and 10 mg/kg/d from day 4–17 significantly reduced inflammation and enhanced barrier function by suppressing the IL-6/STAT3 pathway." (PMID 41158126, 2025). "Additionally, elevated expression of IFNG-AS1 has been associated with activation of IFN-γ, IL-1, IL-6, and TNF-α in ulcerative colitis specimens." (PMID 40658679, 2025). "Fibroblasts from patients with ulcerative colitis produce IL-6 upon stimulation by IL-17." (PMID 38788669, 2025). "For instance, cecropin A not only effectively reduced the levels of proinflammatory factors TNF-α, IL-6, and IL-1β in the colon tissues of mice with ulcerative colitis but also reduced the E. coli-induced expression of IL-6, IL-8, and TNF-α mRNAs in porcine intestinal epithelial cells (IPEC-J2)." (PMID 41099619, 2025). "Additionally, podophyllotoxin significantly lowered the levels of inflammatory cytokines (TNF-α, IL-1β, IL-6) in the serum and colonic tissues of ulcerative colitis model mice and improved oxidative stress status." (PMID 40432443, 2025). "Glycyrrhiza uralensis alleviated intestinal inflammation by inhibiting pro-inflammatory factors (e.g., IL-6 and IL-1β), and mitigated ulcerative colitis by repairing mitochondrial damage and increasing SOD, GSH-PX, and IL-10 levels in intestinal epithelial cells." (PMID 41180229, 2025). "In addition, NCAPD3‐induced activation of IKK/NF‐κB pathway and secretion of proinflammatory cytokines TNF‐α/IL‐6 promote the development of ulcerative colitis." (PMID 39917394, 2025). "To investigate the effects of DID on the expression of inflammatory factors and intestinal barrier protein in colonic tissues of mice with DSS-induced ulcerative colitis, we detected the expressions of IL-6, IL-1β and TNF-α in DSS-stimulated colon tissues via Western blot." (PMID 39452928, 2024). "Related to that, an increase in the main pro-inflammatory markers such as TNF-α and IL-6, together with an increase in the relative abundance of Alloprevotella, were detected in a mice model of ulcerative colitis, suggesting altogether the possible role of this genus in inflammatory status." (PMID 38999973, 2024). "Methods and Results: Our results indicated that didymin could alleviate the symptoms of ulcerative colitis, as it inhibited the expressions of interleukin-6 (IL-6), interleukin-1β (IL-1β) and tumor necrosis factor-α (TNF-α)." (PMID 39452928, 2024). "Furthermore, it reduced the excessive expression level of interleukin 6 (IL-6), which can be used to improve the symptoms of ulcerative colitis." (PMID 37496821, 2023). "Furthermore, these results agree with previous research conducted in rat models of ulcerative colitis, where concentrations of IL-6 were significantly lower in the Bevacizumab-treated group compared to the control group." (PMID 38313162, 2023). "The present result is in harmony with the earlier results of Trivedi and Jena, who showed that β-carotene administration decreased inflammation combined with ulcerative colitis in mice by lowering the colonic contents of immunomodulatory cytokines IL-17, IL-6, and TNFα." (PMID 37018237, 2023).
ulcerative colitis (continued). "Our study shows higher levels of SE, CRP, Ag PLT ASPI, Ag PLT TRAP, Ag PLT ADP, Le, PLT, FCP, TNF-α, and IL-6 in patients with ulcerative colitis, when compared to the healthy controls, as well as lower levels of vitamins B12, B6, serum Fe, and transferrin saturation." (PMID 36984554, 2023). "Some clinical and pre-clinical studies also demonstrated that ulcerative colitis could lead to a significant increase in serum inflammatory factors, such as IL-17A, IL-6 and CRP." (PMID 35267960, 2022). "Aspirin inhibited carcinogenesis of intestinal mucosal cells in the ulcerative colitis model by inhibiting the interleukin-6/Janus kinase/signal transducer and activator of transcription 3 signaling pathway and promoted apoptosis, thereby suppressing proliferation." (PMID 35946886, 2022). "In the current ulcerative colitis model, the increased expression of mTOR and IL-6 in the colon of ulcerative rats enhanced the generation of Th17 cells and the release of IL-17 and IL-23 in line with reducing the expression of IL-10, the anti-inflammatory cytokine." (PMID 34489707, 2021). "Oscillibacter that showed lower abundance in GIST and intestinal adenocarcinoma in our study, is related to metabolic and inflammatory diseases, with lower levels seen in obese individuals and high abundances in ulcerative colitis mice that correlate with serum interleukin IL6 and IL- levels." (PMID 33596997, 2021). "A previous study also reported that S. boulardii could reduce TNF-α and IL-6 levels in mice ulcerative colitis carcinogenesis model." (PMID 33292591, 2020). "For example, Oscillibacter, which is enriched in mice with ulcerative colitis, is significantly positively correlated with the IL-6 and IL-1β levels, which implies that the gut microbiota might orchestrate immunity by regulating the secretion of cytokines." (PMID 33469451, 2020). "Western blot analysis and qPCR analysis in IEC6 cells stimulated by IL-6 in vitro revealed that EHLJ7 could cooperate with butyrate to exert its anti-ulcerative colitis effect by inhibiting the activation of JAK2/STAT3/SOCS1 pathway." (PMID 32038241, 2019). "As published serum levels of IL-6 and its soluble receptors sIL-6R and sgp130 in IBD are from small cohorts and partly contradictory, we systematically evaluated IL-6, sIL-6R and sgp130 levels as markers of disease activity in Crohn’s disease (CD) and ulcerative colitis (UC)." (PMID 29748708, 2018). "Therefore, the aim of the present study was to systematically analyse IL-6 and sIL-6R serum levels in a large all-comer cohort of outpatients with CD and ulcerative colitis (UC) and healthy control individuals." (PMID 29748708, 2018). "In cytokine-stimulated Caco-2 cells CORM-2 regulates metalloproteinase-7 expression by inhibiting the IL-6 gene and downregulation of IL-8 which could be responsible for a partial resolution of ulcerative colitis and Crohn's disease in vivo." (PMID 26460608, 2015). "In addition, the activity of proinflammatory cytokines such as tumor necrosis factor α (TNF-α), interleukin 1β (IL-1β), and IL-6 is increased in the colonic mucosa of patients with ulcerative colitis." (PMID 24971344, 2014). "The sustained induction of IL-6 by the epithelial cells observed here and the modulation of this in the presence of monocytic cells is similar to what has been reported for chronic inflammatory diseases of the gut, Crohns disease and ulcerative colitis." (PMID 24238294, 2013). "Furthermore, RASSF1A epigenetic silencing can be detected in ulcerative colitis patients 22 and upon IL-6 production." (PMID 24146755, 2013). "Additionally, AGN extract prevented epithelial injury in colonic tissues of a murine model of dextran sulfate sodium-induced ulcerative colitis by moderating the activation of inflammatory mediators, such as IL-6, TNF-α, prostaglandin E2 (PGE2), and cyclooxygenase-2 (COX-2)." (PMID 32823713, 2020).
ulcerative colitis (continued). "Moreover, a number of reports indicated that 5-AZA altered DNA binding activation of NF-κB in macrophage, reversed inflammation (COX-2) in Epstein-Barr Virus-positive gastric epithelial cells and inhibited IL-6 in a cohort of ulcerative colitis patients with varying degrees of dysplasia." (PMID 23717425, 2013). "The inhibitory effect of CP on TNF-α was previously demonstrated in a murine model of peritonitis and ulcerative colitis, in which CP doses of 40 mg/kg reduced IFN-γ, IL-6, and TNF-α levels." (PMID 40142455, 2025). "Similar inhibitory effects on NF-κB, IL-6, and TNF-α have been observed in Dextran Sodium Sulfate (DSS)-induced ulcerative colitis models." (PMID 40869259, 2025). "Astragalus polysaccharide significantly alleviates colonic damage in ulcerative colitis by inhibiting pro-inflammatory factors (TNF-α, IL-6, IL-1β) and oxidative stress products (MDA) and restoring the activity of antioxidant enzymes (SOD)." (PMID 41395463, 2025). "In rats with ulcerative colitis, low doses of PC administered orally for one week decreased the expression of TNF-α, IL-1β, and IL-6 and increased the level of transforming growth factor (TGF)-β, which is essential for healing of the intestinal mucosa." (PMID 40498951, 2025). "Ferroptosis is known to provoke inflammatory responses, with research showing that inhibiting ferroptosis can reduce the release of IL-6 and COX-2 in ulcerative colitis." (PMID 40455823, 2025). "In parallel with current results, inhibition of iNOS in patients with ulcerative colitis decreased mucosal TNF-α and IL-6 production and promoted ulcer healing and positive prognosis." (PMID 40644360, 2025). "The classic TCM formulaSi-Wu decoction significantly decreases the levels of IL-6, TNF-α, and IL-1β, effectively treating ulcerative colitis." (PMID 38379418, 2024). "In a rat model of ulcerative colitis, the authors found that intervention with Quercus brantii gel significantly improved inflammatory markers such as TNF‐α, and IL‐6." (PMID 39479683, 2024). "L. plantarum decreased the levels of IL-1β, IL-6, TNF-α, and IFN-γ to enhance the immune barrier and effectively improve ulcerative colitis." (PMID 38540864, 2024). "Existing study has shown that BA can significantly alleviate ulcerative colitis induced by 2,4,6-trinitrobenzene sulfonic acid (TNBS) by blocking the PI3K-AKT signaling pathway, thereby reducing the release of IL-6, TNF-α, and IL-1β." (PMID 39104394, 2024). "COST decreased the expression of IL1- β, IL-6, and TNF-α in a murine model of acute ulcerative colitis, according to another study." (PMID 38629103, 2024). "Akkermansia muciniphila can also improve DSS-induced ulcerative colitis by regulating some key inflammatory response components, including TNF-α, IL-6 and other pro-inflammatory cytokines." (PMID 39452928, 2024). "In chronic inflammatory conditions such as ulcerative colitis, T. erecta has shown effectiveness by reducing TNF-α and IL-6 levels." (PMID 38139287, 2023). "Inflammatory factors such as IL-1b, IL-6, TNF-α, iNOS, and COX-2, are frequently expressed in ulcerative colitis models." (PMID 37375714, 2023). "SA also effectively ameliorated ulcerative colitis in rats by suppressing TNF-α, interleukin 6 (IL-6), Myeloperoxidase (MPO), Prostaglandin E2 (PGE2), cyclooxygenase-2 (COX-2), and NF-κB." (PMID 37444374, 2023). "Inflammatory cytokines and mediators, such as IL-1b, IL-6, TNF-α, iNOS, and PGE2, are involved in inflammatory responses that induce ulcerative colitis in patients with intestinal inflammation." (PMID 37375714, 2023). "For the crude extract, the ethanol extract of LA-R diminished the production and secretion of interleukin (IL)-6, regulated IL-6/STAT3 signal transduction, and modulated the balance of T helper (Th) 17 and Treg cells to attenuate ulcerative colitis." (PMID 36726818, 2022).
ulcerative colitis (continued). "Oroxylin A as the main component extracted from Scutellariae radix can decrease the expression of inflammatory cytokines IL-6 and IL-1β, and attenuated IL-6/STAT3 signaling pathway in ulcerative colitis mice." (PMID 34997010, 2022). "Cavidine improved ulcerative colitis by regulating the oxidation and antioxidant balance and inhibiting NF-κB signaling pathways and pro-inflammatory cytokines, such as TNF-α and IL-6, in colonic tissue." (PMID 35631773, 2022). "Previous studies in ulcerative colitis have demonstrated that blocking IL-1R2 upregulated the expression of pro-inflammatory chemokines induced by Il-1β, such as TNF-a, IL-6 and IFN-γ." (PMID 35087030, 2022). "Multiple studies included in this study showed that vitamin D supplementation effectively reduced the levels of inflammatory factors (IL-6, TNF-α, and CRP) in patients with ulcerative colitis." (PMID 35912148, 2022). "The inflammatory response affects the formation of ulcerative colitis and increases the production of proinflammatory cytokines such as TNF-α, IL-1β, IL-6, and IFN-γ11,40." (PMID 35894303, 2022). "It suggested that the free polyphenol extract of cherry likely acted as the inhibitor of IL-6 and TNF-α but the promotor of IL-10, and thus contributed to relieve ulcerative colitis induced by DSS in a cytokine-specific manner." (PMID 35010176, 2021). "In a mice model of ulcerative colitis, polydatin targets the NF-κB-p65 pathway and exerts an anti-inflammatory effect by blocking the expression of the main inflammatory cytokines TNF-α, IL-6, and IL-1β." (PMID 34887932, 2021). "Oat beta-glucan has also been previously shown to decrease the mRNA and protein expression of pro-inflammatory cytokines such as IL-1β, IL-6, and TNF-α in mice suffering from dextran sulfate sodium (DSS)-induced ulcerative colitis." (PMID 32707913, 2020). "It is well known that ulcerative colitis is characterized by the production of a wide range of inflammatory cytokines, including TNF-α, IL-1β, and IL-6." (PMID 31827675, 2019). "In DSS-induced ulcerative colitis, it is well known that the expression of iNOS and COX-2 is upregulated, followed by the increased expression of pro-inflammatory cytokines such as IL-6 and TNF-α." (PMID 31569788, 2019). "UroA/UAS03 treatment also reduced neutrophil infiltration as evident from myeloperoxidase (MPO) activity as well as serum inflammatory markers such as IL-6, TNF-α, CXCL1, and IL-1β that are hallmarks of ulcerative colitis." (PMID 30626868, 2019). "Intestinal inflammation intensity in the ulcerative colitis is positively correlated with TLR8 and inflammatory cytokines such as IL-6 and TNF-α." (PMID 30044791, 2018). "In a mouse model of ulcerative colitis, which was induced by dextran sulfate sodium, expressions of TNF-α, IL-1β, and IL-6 were markedly up-regulated in the colon, resulting in intestinal mucosal inflammation." (PMID 29694505, 2018). "Since DSS induced ulcerative colitis, the expressions of three proinflammatory cytokines (TNF-α, IL-6, and IL-1β) were examined in the serum and colorectum tissue." (PMID 29483924, 2018). "The results are in accordance with an earlier study where Lactobacillus delbrueckii and Lactobacillus fermentum ameliorated the inflammation by decreasing concentration of IL-6 and expression of TNF-α and NF-κB p65 in ulcerative colitis." (PMID 24966470, 2014). "Recently, we reported that production of pro-inflammatory cytokines, IL-1β, IL-6, and TNF-α, was significantly decreased by oral administration of L. plantarum K68 in DSS-induced ulcerative colitis mice." (PMID 23690866, 2013). "IL-1β stimulates the production of the pro-inflammatory cytokine IL-6 which has been described to be up-regulated in mouse model of IBD and in human ulcerative colitis or Crohn’s disease patients." (PMID 23198878, 2012).
ulcerative colitis (continued). "In contrast, pro-inflammatory markers (IL6, CD68, CD15, TLR4) expression is higher in adenocarcinoma tissues respect to the adenoma, the ulcerative colitis and the healthy tissues." (PMID 21059221, 2010). "This is consistent with the fact that IL6 and IL8 levels in the lumen and in inflamed mucosa are related to severity of disease in ulcerative colitis and Crohn's disease." (PMID 21318186, 2010). "That disease activity correlated with circulating concentrations of IL17, IL10, IL8, IL6 and interferon‐γ when assessed in cross‐sections of patients with ulcerative colitis is not new, as was the poor correlation with levels of TNFα." (PMID 40584280, 2025). "In addition, 12-week treatment with S. boulardii improved azoxymethane and DSS-induced ulcerative colitis (UC) carcinogenesis in C57BL/6J mice, which was attributed to a decrease in colon TNFα and IL-6 levels." (PMID 40872558, 2025). "Decreased plasma levels of hs-CRP, TNF-α, plasma DA0, ET, D-lactic acid, IL-8, and IL-6 and increased CD4/CD8 ratio and CD4+ levels, enhancing the remedying impact in ulcerative colitis patients and regulating T cell frequency, in addition to reducing plasma inflammatory factors." (PMID 38398870, 2024). "Pharmacological research shows that a 90% ethanol extract of D. lablab flowers can also significantly suppress the expression of inflammatory cytokines such as IL-6, TNF-α, and IL-1β in a mice model of ulcerative colitis and promote the recovery of intestinal epithelial tight junctions." (PMID 39202831, 2024). "As an ingredient in TCM with dual applications in both medicinal treatment and dietary consumption, D. lablab flowers have been reported to significantly suppress the expression of inflammatory cytokines such as IL-6, TNF-α, and IL-1β in a mice model of ulcerative colitis." (PMID 39202831, 2024). "Zhao Tian-yu reported that a Phellinus igniarius polysaccharide (A3) with an α-1, 6-D-GALp structure could significantly reduce IL-6, IL-1β, and TNF-α mRNA expression in RAW264.7 cells and mice with LPS-induced ulcerative colitis." (PMID 39202931, 2024). "Oral administration of C. bovis was also found to alleviate the inflammatory damage in the colon tissue of mice ulcerative colitis model induced by dextran sulfate sodium, accompanied by reduced levels of myeloperoxidase, SOD, and mRNA expression of IL-1β, IL-6, and TNF-α." (PMID 36903252, 2023). "Also, berberine exhibited a similar tendency and reduced the IL-1beta, IL-6, and TNF-alpha levels in the study on mice with induced ulcerative colitis, at a dose of 100 mg/kg b.w. i.g.." (PMID 37108329, 2023). "Our findings also reinforced the significance of these inflammatory factors in the incidence and progression of ulcerative colitis, and also demonstrated that SP could drastically lower the iNOS, TNF-α and IL-6 levels in UC mice." (PMID 36838515, 2023). "The present study found that APH reduced the inflammatory response by upregulating the content of IL-10 and downregulating the content of TNF-α, IL-1β, and IL-6, which demonstrates that APH could alleviate ulcerative colitis." (PMID 36359970, 2022). "In addition, using an ulcerative colitis mice model, GA reduced IL-6 and IL-1β, regulating the phosphorylation of NF-κB and IkB-α, and the expression of COX-2 and PGE2 in an ulcerative colitis model." (PMID 35456938, 2022). "The data demonstrated that LREE could significantly inhibit the production of IL-6 and phosphorylation of STAT3, JAK1, JAK2 in ulcerative colitis model mice." (PMID 34093175, 2021). "In addition, in people suffering from ulcerative colitis, the levels of TNF-α, IL-6, and IL-1β are greatly increased in the mucosa and serum." (PMID 33204254, 2020). "Therefore, for ulcerative colitis with the existence of IL-1βand TNF-α, the production pathway of HIF-1α is more abundant, and the activation of HIF-1α can induce the production of IL-6, IL-8 and other inflammatory mediators such as iNOS and COX-2." (PMID 32600331, 2020).